PLA2R1 (phospholipase A2 receptor 1)
Description:
Receptor for secretory phospholipase A2 (sPLA2). Acts as a receptor for phospholipase sPLA2-IB/PLA2G1B but not sPLA2-IIA/PLA2G2A. Also able to bind to snake PA2-like toxins. Although its precise function remains unclear, binding of sPLA2 to its receptor participates in both positive and negative regulation of sPLA2 functions as well as clearance of sPLA2. Binding of sPLA2-IB/PLA2G1B induces various effects depending on the cell type, such as activation of the mitogen-activated protein kinase (MAPK) cascade to induce cell proliferation, the production of lipid mediators, selective release of arachidonic acid in bone marrow-derived mast cells. In neutrophils, binding of sPLA2-IB/PLA2G1B can activate p38 MAPK to stimulate elastase release and cell adhesion. May be involved in responses in pro-inflammatory cytokine productions during endotoxic shock. Also has endocytic properties and rapidly internalizes sPLA2 ligands, which is particularly important for the clearance of extracellular sPLA2s to protect their potent enzymatic activities. The soluble secretory phospholipase A2 receptor form is circulating and acts as a negative regulator of sPLA2 functions by blocking the biological functions of sPLA2-IB/PLA2G1B. In podocytes, binding of sPLA2-IB/PLA2G1B can regulate podocyte survival and glomerular homeostasis.
Synonyms: PLA2-R; PLA2R; CLEC13C; PLA2G1R; PLA2IR
Tractability: Antibody: UniProt places it where antibodies can reach, with high confidence; its Gene Ontology location is reachable by antibodies, with high confidence; UniProt predicts a signal peptide or a membrane-spanning region. PROTAC: ubiquitination databases record sites on it.
Gene: Protein-coding gene on chromosome 2 (159,932,006 to 160,062,636, reverse strand). Ensembl gene ENSG00000153246.
Subcellular location: Cell membrane; Secreted (Soluble secretory phospholipase A2 receptor); Secreted (Isoform 2)
Subcellular location (Human Protein Atlas): Cytosol; Predicted to be secreted
Pathways (Reactome):
Metabolism: Acyl chain remodelling of PC; Acyl chain remodelling of PE; Acyl chain remodelling of PG; Acyl chain remodelling of PI; Acyl chain remodelling of PS; Synthesis of PA
Gene Ontology:
Molecular function: phospholipase A2 inhibitor activity; transmembrane signaling receptor activity; phospholipase binding
Biological process: oxidative stress-induced premature senescence; positive regulation of cytokine production; positive regulation of podocyte apoptotic process; reactive oxygen species metabolic process; replicative senescence; negative regulation of arachidonate secretion; positive regulation of arachidonate secretion; receptor-mediated endocytosis
Cellular component: cell surface; plasma membrane; receptor complex; extracellular region
Genetic constraint (gnomAD): Loss-of-function variants: 72 observed, 87.63 expected, observed/expected ratio (o/e) 0.82, 90% interval 0.68 to 1. The upper end of that interval is the gene's LOEUF score, 1, which puts it in group 4 of 6, group 1 being the genes least tolerant of losing a copy. Missense variants: 884 observed, 983.11 expected, observed/expected ratio (o/e) 0.9, 90% interval 0.85 to 0.95. Synonymous variants: 348 observed, 349.82 expected, observed/expected ratio (o/e) 0.99, 90% interval 0.91 to 1.09.
Homologues: Orthologues: chimpanzee PLA2R1 (99% identical), macaque PLA2R1 (96% identical), dog PLA2R1 (85% identical), pig PLA2R1 (83% identical), rabbit PLA2R1 (83% identical), guinea pig PLA2R1 (77% identical), mouse Pla2r1 (74% identical), rat Pla2r1 (73% identical), tropical clawed frog pla2r1 (44% identical), zebrafish pla2r1 (39% identical). Paralogues in human: LY75 (33% identical), MRC2 (33% identical), MRC1 (28% identical), CD302 (3% identical).
Diseases named in the same sentence as PLA2R1 in open-access papers:
PLA2R1 is named in the same sentence as 192 diseases in open-access papers, as found by Europe PMC text mining. Sharing a sentence is not in itself a finding about the gene and the disease. The quoted sentences say what the papers report.
membranous nephropathy (248 papers, 2012 to 2026). "The purpose of this study was to observe the relationship between gene polymorphisms and primary membranous nephropathy and explore the clinical functional clues of PLA2R1 and HLA-DQA1 genes affecting treatment responsiveness." (PMID 40845005, 2025). "Among the patients with PLA2R1-associated membranous nephropathy, 12 patients (92%) in the obinutuzumab or ofatumumab group and 9 patients (56%) in the rituximab group achieved immunological remission at month 6 (P = 0.04)." (PMID 40225374, 2025). "Among patients with PLA2R1-associated membranous nephropathy, 10 patients (83%) in the obinutuzumab or ofatumumab group and 7 patients (47%) in the rituximab group achieved immunological remission at month 12 (P = 0.1)." (PMID 40225374, 2025). "Stratification of patients requiring immunosuppressive treatment according to the clinical and/or immunological severity of their disease has become a vital part of treatment decision making for patients with PLA2R1-associated membranous nephropathy." (PMID 41324008, 2025). "Membranous nephropathy is a renal autoimmune disease associated with autoantibodies against phospholipase A2 receptor (PLA2R1) in 50–80% of cases." (PMID 41324008, 2025). "An individualized immunomonitoring and management strategy for kidney transplant candidates with anti-PLA2R1-associated membranous nephropathy should be considered." (PMID 39698349, 2024). "Patients with recurrent membranous nephropathy had significantly higher levels of anti PLA2R1 antibodies in enzyme-linked immunosorbent assay at transplantation than those who did not relapse: 12 (IQR: 2–51) RU/ml versus 2 (IQR: 2–2) RU/ml, P = 0.0002." (PMID 39698349, 2024). "First, the predictive value of anti-PLA2R1 antibodies is of interest only for patients with anti-PLA2R1-associated membranous nephropathy." (PMID 39698349, 2024). "In this study, we evaluated the value of baseline anti–phospholipase A2 receptor (PLA2R1) antibody titer as a prognostic biomarker in patients with PLA2R1-associated membranous nephropathy." (PMID 34169209, 2021). "Several variants in PLA2R1 have previously been associated to membranous nephropathy, and serum anti-PLA2R1 antibody associates with loss of kidney function." (PMID 34079037, 2021). "Membranous nephropathy (MN) is an autoimmune disease caused by autoantibodies against the podocyte antigens phospholipase A2 receptor 1 (PLA2R1) and thrombospondin type 1 domain containing protein 7A (THSD7A) in 80% and 2–3% of patients, respectively." (PMID 34376704, 2021). "In contrast, genetic variation in PLA2R1 has been associated with membranous nephropathy; a risk allele at HLA-DQA1 has also been associated with increased risks of various autoimmunity-associated diseases, but not IgAN17." (PMID 32820208, 2020). "Membranous Nephropathy (MN) is an autoimmune disease associated with antibodies against podocyte proteins: M-type phospholipase A2 receptor (PLA2R1) or thrombospondin type-1 domain-containing 7A (THSD7A) in 70 and 3% of patients, respectively." (PMID 31998325, 2019). "(vi) Approximately 50% of cases of recurrent membranous nephropathy after kidney transplantation are associated with anti-PLA2R1 antibodies." (PMID 29511687, 2018). "In this study, we found several PLA2R1 and HLA-DQA1 single-nucleotide polymorphism loci associated with primary membranous nephropathy morbidity and that some PLA2R1 single-nucleotide polymorphism loci were related to the treatment response of patients with primary membranous nephropathy." (PMID 40845005, 2025). "The development of PLA2R1-related membranous nephropathy is most likely influenced by genetic susceptibility, loss of tolerance, and changes in antigen expression, but environmental factors such as air pollution, heavy metal poisoning, smoking and infection also play an important role." (PMID 39497816, 2024).
membranous nephropathy (continued). "Interestingly, several variants in PLA2R1 have previously been associated to membranous nephropathy, and serum anti-PLA2R1 antibody associates with loss of kidney function." (PMID 34079037, 2021). "(iii) The presence of anti-PLA2R1 antibodies has been reported in membranous nephropathy associated with secondary conditions (hepatitis B virus, membranous form of lupus nephritis, sarcoidosis, or malignancy); however their significance remains a matter of debate." (PMID 29511687, 2018). "Another renal AID, i.e., membranous nephropathy (MN), is characterized by the presence of autoantibodies targeting phospholipase A2 receptor 1 (PLA2R1) and thrombospondin type-1 domain-containing protein 7A (THSD7A)." (PMID 40422256, 2025). "GL is a co-inventor on the patents “Diagnostics for membranous nephropathy” and “Profiling of immunodominant PLA2R1 epitopes as a prognosis and predictive factor in membranous nephropathy”." (PMID 41324008, 2025). "Thrombospondin type‐1 domain‐containing 7A (THSD7A) is a large transmembrane glycoprotein like PLA2R1, and again like PLA2R1 was recently identified as a novel podocyte foot process protein targeted by autoimmunity in membranous nephropathy." (PMID 40698593, 2025). "M‐type phospholipase A2 receptor 1 (PLA2R1 or PLA2R1) was discovered 2009 as a new podocyte foot process protein targeted by autoimmunity in membranous nephropathy, which in the kidney is only expressed by podocytes." (PMID 40698593, 2025). "A genome-wide association study has shown that variants in PLA2R1 and HLA-DQA1 are strongly associated with idiopathic membranous nephropathy in patients of European descent." (PMID 40363910, 2025). "The primary objective was to evaluate the prognostic significance of pretransplant anti phospholipase A2 receptor 1 (PLA2R1) antibodies on the recurrence of membranous nephropathy." (PMID 39698349, 2024). "Membranous nephropathy (MN) is an antibody-mediated autoimmune glomerular disease in which PLA2R1 is the main autoantibody." (PMID 39497816, 2024). "PLA2R1 has been reported in a series of studies on membranous nephropathy and is widely used in clinical practice." (PMID 38836837, 2024). "The presence of anti-PLA2R1 antibodies prior to transplantation was a strong predictor of recurrence of allograft membranous nephropathy." (PMID 39698349, 2024). "The main objective was to assess the prognostic role of pretransplant anti-PLA2R1 antibodies for membranous nephropathy recurrence after kidney transplantation." (PMID 39698349, 2024). "A meta-analysis showed that the sensitivity and specificity of serum anti-PLA2R1 in diagnosing idiopathic membranous nephropathy were 68% and 97%, respectively." (PMID 38836837, 2024). "Our study is the first to report that APC can improve membranous nephropathy by affecting podocyte apoptosis through the ERK1/2/YB-1/PLA2R1 axis." (PMID 36588134, 2023). "Testing for antibodies against podocyte phospholipase A2 receptor-1 (PLA2R) allows clinicians to accurately identify primary membranous nephropathy (MN)." (PMID 34592934, 2021). "Our study questions the relevance of single measurement of anti-PLA2R1 antibodies at baseline as a prognostic biomarker in membranous nephropathy." (PMID 34169209, 2021). "This would indicate that the signal reported in these previous membranous nephropathy genetic studies at the PLA2R1 locus is the same as for suPAR in our study." (PMID 34079037, 2021). "Phospholipase A2 receptor 1 (PLA2R1) and thrombospondin type-1 domain-containing 7A (THSD7A) are the two major pathogenic antigens for membranous nephropathy (MN)." (PMID 34229600, 2021). "In other autoimmune diseases such as SLE, IgG4-related disease, and anti-PLA2R1 related membranous nephropathy the plasmablast frequency has been reported to be related to disease activity, as were absolute plasmablast numbers in SLE and IgG4-related disease." (PMID 31608054, 2019).
membranous nephropathy (continued). "Membranous nephropathy (MN) is an autoimmune disease induced by circulating antibodies against the podocyte protein phospholipase A2 receptor 1 (PLA2R1-ab) in 80% of patients and represents the leading cause of nephrotic syndrome in adults." (PMID 31498806, 2019). "Membranous nephropathy (MN) is a kidney specific autoimmune disease mainly mediated by anti-phospholipase A2 receptor 1 autoantibody (PLA2R1 Ab)." (PMID 27493452, 2016). "Genotypic and allelic frequency distributions for six single-nucleotide polymorphisms within PLA2R1 (rs4664308, rs3792189, rs3792192, rs1870102, rs17831251, and rs35771982) and one in HLA-DQA1 (rs2187668) were associated with morbidity of primary membranous nephropathy." (PMID 40845005, 2025). "Among the risk factors for posttransplant membranous nephropathy recurrence, only the high levels of anti-PLA2R1 antibodies, although the threshold is not defined, seems to be consensual." (PMID 39698349, 2024). "In addition, there is insufficient data on preventive treatment, including rituximab, for patients with membranous nephropathy and high levels of anti-PLA2R1 on the waiting list." (PMID 39698349, 2024). "Thus, our study is the first to report that APC can improve membranous nephropathy by affecting podocyte apoptosis through the ERK1/2/YB-1/PLA2R1 axis." (PMID 36588134, 2023). "Therefore, our study is the first to report that APC can ameliorate membranous nephropathy by affecting podocyte apoptosis through the ERK1/2/YB-1/PLA2R1 axis." (PMID 36588134, 2023). "Finally, PLA2R1 has been identified as the major autoantigen in membranous nephropathy (MN), a rare autoimmune kidney disease." (PMID 32424163, 2020). "Additionally, glomerular transcriptomics identified PLA2R1 expression as being increased in membranous nephropathy in the parenteral administration of the Fn14 ligand TWEAK increased podocyte PLA2R expression in mice." (PMID 32664235, 2020). "(vii) Recently, epitope spreading within anti-PLA2R1 antibodies, levels of regulatory T cells, circulating plasmablasts, and plasma cells emerged as interesting additional tools for monitoring of immunological activity in primary membranous nephropathy." (PMID 29511687, 2018). "The potentially non-essential role of PLA2R1 in overall human health might explain why this gene is specifically associated with membranous nephropathy (PLA2R1-MN) but not linked to a broader range of diseases." (PMID 40149392, 2025). "Finally, over the last decade, PLA2R1 has attracted much attention in membranous nephropathy (MN), a rare but severe autoimmune kidney disease in which PLA2R1 was identified as the major autoantigen, with circulating anti-PLA2R1 autoantibodies present in a majority of MN patients." (PMID 38897568, 2024). "The aim of this study was to demonstrate the relationship between the PLA2R1 and HLA-DQA1 genes and PMN and to determine the clinical value of SNP in the treatment of primary membranous nephropathy." (PMID 40845005, 2025). "Phospholipase A2 receptor 1 (PLA2R1) is a 180-kDa transmembrane protein that plays a role in inflammation and cancer and is the major autoantigen in membranous nephropathy, a rare but severe autoimmune kidney disease." (PMID 38897568, 2024). "Serum and tissue-based tests using phospholipase A2 receptor 1 (PLA2R) and thrombospondin type-1 domain containing 7A (THSD7A) are established immune biomarkers for the diagnosis of primary membranous nephropathy (PMN)." (PMID 33413188, 2021). "Patients with recurrent membranous nephropathy had significantly higher levels of anti-PLA2R1 antibodies at transplantation than those who did not relapse: 60 (IQR: 16–226) RU/ml versus 2 (IQR: 2–12) RU/ml, P < 0.0001." (PMID 39698349, 2024).
membranous nephropathy (continued). "The identification of the phospholipase A2 receptor 1 (PLA2R) and thrombospondin type-1 domain-containing protein 7A (THSD7A) as podocyte antigens in adult patients with membranous nephropathy (MN) has strongly impacted both experimental and clinical research on this disease." (PMID 33825066, 2021).
nephrotic syndrome (86 papers, 2014 to 2026). A collection of symptoms that include severe edema, proteinuria, and hypoalbuminemia; it is indicative of renal dysfunction. "High baseline or increasing anti-PLA2R1 antibody titers, on the other hand, are associated with persistent nephrotic syndrome and progressive loss of kidney function, which should lead to the prompt initiation of immunosuppressive therapy." (PMID 35603210, 2022). "There was a clear association between anti-PLA2R1 antibody titer and severity of the nephrotic syndrome." (PMID 34169209, 2021). "Several SNPs around the Pla2r1 gene (phospholipase A2 receptor 1) are reported to be significantly associated with idiopathic membranous nephropathy, which is the most common cause of nephrotic syndrome and renal failure." (PMID 32429546, 2020). "Indeed, higher levels of circulating anti-PLA2R1 antibodies strongly correlate with the importance of proteinuria, predict a higher risk of recurrence of nephrotic syndrome and decline of renal function, and are associated with a lower rate and a longer time to obtain remission." (PMID 29511687, 2018). "In this clinical trial, we will compare two therapeutic strategies in patients with PLA2R1-related iMN to induce clinical remission of the nephrotic syndrome." (PMID 32903623, 2020). "As an autoantigen, phospholipase A2 receptor 1 (PLA2R1), a biomarker of idiopathic membranous nephropathy (iMN), plays an important role in adult nephrotic syndrome, which has variable natural history and disease progression." (PMID 29843797, 2018). "Circulating anti-PLA2R1 antibodies reflect immunological activity of disease and have been shown to disappear before clinical remission of nephrotic syndrome and to reappear in the circulation before clinical relapse." (PMID 29511687, 2018). "We used immunohistochemical staining and electron microscopy to investigate the renal biopsies from six patients with nephrotic syndrome and PLA2R1-positive primary MN." (PMID 27855638, 2016). "Thus, according to the KDIGO 2021 guidelines, a kidney biopsy is not required to confirm the diagnosis of pMN in patients with nephrotic syndrome and a positive anti-PLA2R1 antibody test." (PMID 35603210, 2022). "Detection of high PLA2R1 serum titers, which has high sensitivity and specificity for idiopathic membranous nephropathy, was also reported in a study on a patient with type 1 diabetes, diabetic retinopathy, arterial hypertension, and nephrotic syndrome." (PMID 32429546, 2020). "The detection of anti-PLA2R1 antibodies in patients with nephrotic syndrome can be considered as a biomarker for the diagnosis of primary MN according to a recent meta-analysis (all study sensitivity 78% (95% CI: 66% to 87%) and specificity 99% (95% CI: 96% to 100%))." (PMID 29511687, 2018). "In addition, a high anti-PLA2R1 titer at diagnosis was associated with a higher risk of long-term renal impairment and a higher risk of developing nephrotic syndrome in previously non-nephrotic patients." (PMID 35603210, 2022).